NBN (nibrin)
Diseases named in the same sentence as NBN in open-access papers (continued):
Sharing a sentence is not in itself a finding about the gene and the disease.
gastric cancer (6 papers, 2015 to 2025). A primary or metastatic malignant neoplasm involving the stomach. "The most robust SNP rs10464867 (G>A) is located in the 3’ UTR of NBN, having associated with a decreased risk of gastric cancer." (PMID 26402912, 2015). "In current study, rs10464867 located in NBN was identified to be significantly associated with altered risk of gastric cancer in Chinese population." (PMID 26402912, 2015). "In the past decade, a certain number of polymorphisms distributed in NBN gene have been reported to be associated with several different kinds of malignancy other than gastric cancer." (PMID 26402912, 2015). "The base change of G to A for rs10464867 may bring to subtle structural alterations of NBN protein and consequently modulation of gastric cancer susceptibility." (PMID 26402912, 2015). "In summary, these findings indicate that genetic variants at NBN gene may contribute to gastric cancer susceptibility and may further advance our understanding of NBN gene in cancer development." (PMID 26402912, 2015). "Finally, we reported that the NBN gene contains genetic variants associated with risk for gastric cancer." (PMID 26402912, 2015). "The current study provided important clues that genetic variants in NBN might also be involved in the susceptibility of gastric cancer and further highlight the potential pleiotropic effect of NBN SNPs on multiple cancers." (PMID 26402912, 2015). "The NBN gene has been implicated in susceptibility to a high number of cancers, whereas no genetic variants have been reported so far as being associated with gastric cancer." (PMID 26402912, 2015). "Therefore, we conducted a case-control study to investigate the association between four potentially functional single nucleotide polymorphisms (SNPs) in NBN gene and gastric cancer risk with 1,140 gastric cancer cases and 1,547 controls in a Chinese population." (PMID 26402912, 2015). "We hypothesized that genetic variants in the NBN gene may modify the risk of gastric cancer." (PMID 26402912, 2015). "Our data suggest that increased lymphangiogenesis and somatic mutations of NBN and/or PAX8 could facilitate lymph node metastasis from an intramucosal gastric carcinoma." (PMID 29535844, 2018).
anemia (5 papers, 2019 to 2023). A reduction in the number of red blood cells, the amount of hemoglobin, and/or the volume of packed red blood cells. "BRCA1 and 2 interacts with a number of other DNA repair proteins to form a complex system for DNA damage repair, including ATM, RAD51, PALB2, MRE11A, RAD50, NBN, and the Fanconi anemia proteins." (PMID 35785170, 2022).
ataxia telangiectasia (5 papers, 2013 to 2025). Ataxia-telangiectasia is the association of severe combined immunodeficiency (affecting mainly the humoral immune response) with progressive cerebellar ataxia. "Ataxia-telangiectasia (A-T, ATM mutation), the related A-T like disease (ATLD, MRE11 mutation), Nijmegen breakage syndrome (NBS, NBS1/NBN mutation) and the more recently identified NBS like disease (NBSLD, RAD50 mutation), all present with similar pathological outcomes in humans." (PMID 23532176, 2013).
Hereditary breast and ovarian cancer syndrome (5 papers, 2019 to 2025). An autosomal dominant inherited syndrome caused by mutations in the BRCA1 or BRCA2 genes. "The pathogenic mutations in genes such as MUTYH, FANCD2, NBN, PALB2, and BRCA1 are associated with hereditary breast and ovarian cancer syndrome, an autosomal dominant disorder typically manifesting around age 30 and above." (PMID 41229399, 2025).
medulloblastoma (5 papers, 2013 to 2022). A malignant, invasive embryonal neoplasm arising from the cerebellum. "Inherited or somatic mutations in the MRE11, RAD50 and NBN genes increase the incidence of tumours, including medulloblastoma (MB)." (PMID 35839783, 2022). "The evidence that NBN heterozygous variants predispose to childhood acute lymphoblastic leukemia and medulloblastoma was already published." (PMID 28376765, 2017). "Within essential components of DNA repair signaling cascade the NBN gene particularly draws attention as potentially susceptibility marker for medulloblastoma." (PMID 28376765, 2017). "Germline defects in medulloblastoma patients were observed also in other genes cooperated with NBN in BRCA1-associated genome surveillance complex (BASC), including MSH6, PMS2 and MLH1." (PMID 28376765, 2017). "Similarly, ATM, NBN, PALB2, PMS2, PTCH1, and SUFU are tumor suppressor and germline risk genes for medulloblastoma, but CH variants in these genes have not been found in prior studies." (PMID 32508881, 2020).
acute lymphoblastic leukemia (4 papers, 2013 to 2018). Leukemia with an acute onset, characterized by the presence of lymphoblasts in the bone marrow and the peripheral blood. "Our previous studies have provided evidence that the p.I171V mutation in the NBN gene is a risk allele in acute lymphoblastic leukemia in children and in breast, colorectal, and larynx cancer in adult." (PMID 24093751, 2013). "Considering together our results from the current and previous studies of the NBN gene mutations and polymorphisms, we still observed the higher incidence of the p.I171V mutation in acute lymphoblastic leukemia (5/188) than among controls (12/2400) (p<0.0004)." (PMID 24093751, 2013). "In our previous study we showed that the germline p.I171V mutation in NBN may be considered as a risk factor in the development of childhood acute lymphoblastic leukemia (ALL) and some specific haplotypes of that gene may be associated with childhood leukemia." (PMID 24093751, 2013).
colorectal cancer (4 papers, 2013 to 2022). A primary or metastatic malignant neoplasm that affects the colon or rectum. "Recently, a prognostic role for NBN somatic mutations has been suggested in a subset of colorectal cancer although in the study, no rectal cancer was included." (PMID 36552003, 2022).
leukemia (4 papers, 2011 to 2023). A malignant (clonal) hematologic disorder, involving hematopoietic stem cells and characterized by the presence of primitive or atypical myeloid or lymphoid cells in the bone marrow and the blood. "We estimated the frequency of constitutional mutations and polymorphisms in selected regions of MRE11, RAD50, and NBN in the group of 220 children diagnosed with childhood leukemias and controls (n=504/2200)." (PMID 24093751, 2013). "In this study, exons 2, 3, 5, 6, 10 and 13 of the NBN gene, in which most of the already known molecular variants occur, were analyzed in 78 leukemia cases (ALL=46, AML=32)." (PMID 24093751, 2013). "Heterozygous carriers of germline NBN variants may also be at risk for leukemia development, although this is much less characterized." (PMID 37503171, 2023). "Previous studies found some potentially functional SNPs of HR genetic polymorphisms (e.g., RAD51-135 G>C, −172G>T, XRCC2 4234G>C, R188H, XRCC3 T241M and NBN E185Q) to be associated with various types of cancer risks, including cancers of the lung, breast, ovary, leukemia and head and neck." (PMID 21647442, 2011).
rectal cancer (4 papers, 2013 to 2022). A primary or metastatic malignant neoplasm that affects the rectum. "Heterozygous carriers of the NBN c.657del5 mutation have an increased risk of malignant tumor development, especially of breast, prostate, colon and rectal cancers." (PMID 29678143, 2018). "After stratification for tumor site, two polymorphisms in RAD52 gene (rs1051669 and rs11571475) were associated with colon cancer risk while one SNP in NBN (rs14448) was associated with rectal cancer risk." (PMID 26735576, 2016).
chromosomal instability syndrome (3 papers, 2017 to 2023). "Traditionally, the MRE11/RAD50/NBN deficiency causes chromosome instability syndromes in humans." (PMID 37024481, 2023).
glioblastoma (3 papers, 2012 to 2022). The most malignant astrocytic tumor (WHO grade IV). "Among interesting candidate genes retrieved using the FLN, the NBN gene had previously been postulated to have a role in nonglioma forms of cancer, and recent evidence has (independently from the GWA studies) implicated NBN variants in pediatric glioblastoma." (PMID 22384401, 2012). "Given the essential role of APE1, NBN, PTEN, PMS2 and MGMT in adult tumours we explored if these genes also influence outcomes in paediatric high grade gliomas/glioblastomas." (PMID 25026297, 2014). "To evaluate whether APE1, NBN, PMS2, MGMT and PTEN mRNA also have a role in paediatric high grade gliomas we proceeded to investigate mRNA expression in 53 paediatric high grade gliomas and 27 paediatric glioblastomas." (PMID 25026297, 2014).
glioma (3 papers, 2012 to 2017). A benign or malignant brain and spinal cord tumor that arises from glial cells (astrocytes, oligodendrocytes, ependymal cells). "To investigate whether age may influence abnormal DNA repair gene expression, and affect susceptibility to the development of gliomas, we assessed the association between APE1, NBN, PMS2, MGMT and PTEN mRNA expression and age." (PMID 25026297, 2014). "Taken together, the data suggests that low expression of APE1, NBN and PTEN may increase genomic instability, leading to a mutator phenotype that could promote accelerated accumulation of mutations leading to an aggressive glioma phenotype." (PMID 25026297, 2014). "To evaluate the suitability of the antibody used here, we first investigated the protein expression of APE1, NBN, PMS2, and PTEN in LN229 and LN18 human glioma cell lines by Western blot analysis." (PMID 25026297, 2014). "Regarding the glioma report, the authors speculated that APE1 operates in conjunction with other DNA repair molecules, such as NBN, PMS2, MGMT and PTEN, to influence biological and clinical outcomes in glioma." (PMID 28938675, 2017). "Together the data implies that APE1, NBN, PMS2, MGMT and PTEN do not influence paediatric glioma pathogenesis." (PMID 25026297, 2014).
lymphoma (3 papers, 2009 to 2021). A malignant (clonal) proliferation of B- lymphocytes or T- lymphocytes which involves the lymph nodes, bone marrow and/or extranodal sites. "In support of a role of NBN in tumor formation, evidence from mouse models demonstrated that Nbn heterozygosity predisposes cells to malignancies, as they display a wide variety of tumors: liver, mammary gland, prostate, lung as well as lymphomas." (PMID 19523210, 2009). "Other research has shown that mice heterozygous for NBN (the murine homolog of NBS1) developed HCC in addition to lymphomas." (PMID 24349281, 2013).
metastatic tumor (3 papers, 2014 to 2023). "The metastatic tumor harbored somatic mutations in NBN, p.P6S, and PAX8, p.R49H." (PMID 29535844, 2018). "c-Myc is well known to directly regulate the expression of NBN gene involved in DNA double-strand break repair and can result in chromosomal instability, cellular proliferation defects leading to increased more aggressive and metastatic tumor latency." (PMID 25075970, 2014). "Moreover, somatic mutations of NBN, p.P6S, and PAX8, p.R49H were observed in the metastatic tumor." (PMID 29535844, 2018).
mucositis (3 papers, 2014 to 2025). Mucositis is inflammation and damage of the mucous membranes lining the mouth and other parts of the gastrointestinal (GI) tract. "Haplotype analysis for XRCC1 (rs3213245, rs1799782, rs25489 and rs25487), RAD51 (rs1801320, rs1801321) and NBN (rs1805787, rs1805794) and radiation-induced oral mucositis and skin reactions in head and neck cancer patients." (PMID 24594932, 2014).
acute leukemia (2 papers, 2013 to 2022). A clonal (malignant) hematopoietic disorder with an acute onset, affecting the bone marrow and the peripheral blood. "On the other hand some specific NBN haplotypes have been related to increased susceptibility to childhood acute leukemia." (PMID 24093751, 2013). "With this in mind, we decided to simultaneously analyze the alterations in MRE11, RAD50 and NBN genes in Polish children with acute leukemia." (PMID 24093751, 2013).
astrocytoma (2 papers, 2021 to 2025). "The expression of lnc-NBN-1 was greater in grade 2–3 IDHmut astrocytomas than in other tumor categories, and its high expression was associated with better overall survival in the whole cohort (p < 0.0001, log-rank test) but not within any of the diffuse glioma subtypes." (PMID 40346283, 2025).
endometrial cancer (2 papers, 2020 to 2025). Primary or metastatic malignant neoplasm involving the endometrium (mucous membrane that lines the endometrial cavity). "In addition, PVs in BRCA1, BRCA2, and NBN were significantly associated with moderately increased risks for uterine/endometrial cancer." (PMID 31406321, 2020). "The pathogenicity of the NBN and CHEK2 mutations in this case remains unclear, and current literature has not specifically linked these mutations to endometrial cancer risk." (PMID 40356752, 2025).
metastatic prostate carcinoma (2 papers, 2022 to 2024). A carcinoma that arises from the prostate gland and has spread to other anatomic sites. "In metastatic prostate cancer, an expanded HRD panel included patients with mutations to BRCA1, BRCA2, ATM, FANCA, CHEK2, PALB2, NBN, or HDAC2." (PMID 35205643, 2022).
nasopharyngeal carcinoma (2 papers, 2022 to 2026). A carcinoma arising from the nasopharyngeal epithelium. "Meta-analysis results, supported by bioinformatics analyses, indicate potential associations between NBN gene variants and susceptibility to bladder, brain, breast, and nasopharyngeal cancers." (PMID 41797823, 2026).
osteosarcoma (2 papers, 2015 to 2024). A usually aggressive malignant bone-forming mesenchymal neoplasm, predominantly affecting adolescents and young adults. "First of all, although this study suggested that ERCC2 rs1799793 and NBN rs1805794 polymorphisms were associated with osteosarcoma risk, more biological background data are needed to explain our results." (PMID 26101473, 2015). "We found that GA+AA genotype of ERCC2 rs1799793 or GC+CC genotype of NBN rs1805794 were associated with an increased risk of osteosarcoma in females, and the ORs(95%CI) were 2.42(1.20-4.87) and 2.01(1.07-4.23), respectively." (PMID 26101473, 2015). "Our results suggest that ERCC2 rs1799793 and NBN rs1805794 polymorphisms were associated with an increased risk for osteosarcoma, which suggests that NER and HRR pathways modulate the risk of developing osteosarcoma." (PMID 26101473, 2015). "We found that GA+AA genotype of ERCC2 rs1799793 or GC+CC genotype of NBN rs1805794 were associated with an increased risk of osteosarcoma in females, with ORs(95%CI) of 2.42(1.20-4.87) and 2.01(1.07-4.23), respectively." (PMID 26101473, 2015). "Moreover, individuals carrying GC+CC genotype of NBN rs1805794 were correlated with a heavy enhanced risk of osteosarcoma when compared with GG genotype, and the OR(95%CI) was 2.66(1.73-4.08)." (PMID 26101473, 2015). "Conditional logistic regression analyses found that individuals carrying with GA+AA genotype of ERCC2 rs1799793 and GC+CC genotype of NBN rs1805794 were significantly associated with increased risk of osteosarcoma, and the ORs(95%CI) were 1.58(1.03-2.41) and 2.66(1.73-4.08), respectively." (PMID 26101473, 2015). "Moreover, we conducted stratification analysis on the association between ERCC2 rs1799793 and NBN rs1805794 and demographic characteristics in osteosarcoma patients." (PMID 26101473, 2015). "We also found that ERCC2 rs1799793 and NBN rs1805794 may be associated with carcinogenesis of osteosarcoma." (PMID 26101473, 2015). "In conclusion, our study is, to our knowledge, the first to examine prospectively an increased risk role of ten SNPs in DNA repair pathway in osteosarcoma susceptibility, and we found that ERCC2 rs1799793 and NBN rs1805794 polymorphisms modulate the risk of developing osteosarcoma." (PMID 26101473, 2015).
sarcoma (2 papers, 2021 to 2025). A usually aggressive malignant neoplasm of the soft tissue or bone. "Our study, in addition to known PGVs in sarcomas, also showed two unusual PGVs that are not, including DIS3L2 deletion and NBN deletion." (PMID 40243416, 2025).
Alzheimer disease (1 paper, 2016). A progressive, neurodegenerative disease characterized by loss of function and death of nerve cells in several areas of the brain leading to loss of cognitive function such as memory and language. "We found genes that are related to cancer (NBN, FAM84B), Huntington's disease (DCTN4), Parkinson's disease (NUCKS1), Alzheimer's disease (SMC3), amongst others." (PMID 27257970, 2016).
asthma (1 paper, 2026). "Additionally, we found that the association effect estimates of cold were significantly higher among participants with asthma compared with non-asthmatic participants for four proteins (AGRE2, CTSC, EIF5A, and NBN)." (PMID 41541696, 2026).
B-cell precursor acute lymphoblastic leukemia (1 paper, 2025). "The NBN mutation is involved in cell cycle regulation and DNA damage repair, with carriers at increased risk for tumors, including CNS relapse of B-cell precursor acute lymphoblastic leukemia." (PMID 40356752, 2025).
childhood leukemia (1 paper, 2013). An acute or chronic leukemia that occurs during childhood. "In the current study we screened the selected regions, of the MRE11, RAD50 and NBN gene, where most of already known molecular variants occur, among 220 childhood leukemia samples and controls." (PMID 24093751, 2013). "Some specific haplotypes of the NBN gene may be associated with childhood leukemia." (PMID 24093751, 2013).
chondrosarcoma (1 paper, 2023). A malignant cartilaginous matrix-producing mesenchymal neoplasm arising from the bone and soft tissue. "Olaparib decreased cell survival of CH2879 chondrosarcoma cells and the radiosensitivity was associated with mutations in homologous recombination repair genes, such as RAD50, SMARCA2, and NBN." (PMID 36768638, 2023).
Cirrhosis (1 paper, 2020). A chronic disorder of the liver in which liver tissue becomes scarred and is partially replaced by regenerative nodules and fibrotic tissue resulting in loss of liver function. "The homozygous TT genotype at ERCC2 rs238406, CC at XRCC1 rs25487, and GG at NBN rs2735383 were significantly associated with a lower risk of cirrhosis." (PMID 33171788, 2020).
clear cell renal cell carcinoma (1 paper, 2020). "Ten pathogenic or likely pathogenic (P/LP) variants were identified in 11 sporadic clear cell renal cell carcinoma patients (10.38%), including rarely reported ATM (n=1), MUTYH (n=1), NBN (n=1), RAD51D (n=1), and BRCA2 (n=1)." (PMID 33062672, 2020).
diabetes (1 paper, 2024). "NBN may play an important role in DNA damage-induced aging and complications of diabetes because this protein initiates DNA damage response signaling." (PMID 39459569, 2024).
fibrosis (1 paper, 2020). the formation of excess fibrous connective tissue in an organ or tissue in a reparative or reactive process. "Three genetic variations (ERCC2: rs238406, XRCC1: rs25487, NBN: rs2735383) had diverse frequency in CHB patients with liver cirrhosis and with no fibrosis, highlighting their possible role in HBV-induced liver disease progression." (PMID 33171788, 2020).
gastric adenocarcinoma (1 paper, 2015). "Our analysis based on TCGA (The Cancer Genome Atlas) data further revealed that the NBN mRNA expression level in gastric adenocarcinoma was significantly higher than adjacent normal tissues, suggesting a potential vital role of NBN in gastric carcinogenesis." (PMID 26402912, 2015).